TGIF2LX (TGFB induced factor homeobox 2 like X-linked)
Description:
May have a transcription role in testis.
Synonyms: TGIFLX
Tractability: No criterion of Open Targets' tractability assessment is met for any kind of drug.
Gene: Protein-coding gene on chromosome X (89,921,908 to 89,922,883, forward strand). Ensembl gene ENSG00000153779.
Subcellular location: Nucleus
Subcellular location (Human Protein Atlas): Nucleoplasm
Gene Ontology:
Molecular function: sequence-specific double-stranded DNA binding; DNA-binding transcription factor activity, RNA polymerase II-specific; DNA-binding transcription repressor activity, RNA polymerase II-specific; RNA polymerase II cis-regulatory region sequence-specific DNA binding; DNA binding
Biological process: negative regulation of transcription by RNA polymerase II; regulation of DNA-templated transcription
Cellular component: chromatin; nucleus
Homologues: Orthologues: chimpanzee TGIF2LX (98% identical), macaque TGIF2LX (85% identical), dog TGIF2LX (59% identical), rat Tgif2lx2 (41% identical), mouse Tgif2lx1 (39% identical), mouse Tgif2lx2 (39% identical), Drosophila melanogaster achi (27% identical), Drosophila melanogaster vis (27% identical), Caenorhabditis elegans ceh-60 (16% identical), Caenorhabditis elegans unc-62 (15% identical), Drosophila melanogaster hth (15% identical), Caenorhabditis elegans ceh-20 (12% identical), and 3 more. Paralogues in human: TGIF2LY (65% identical), TGIF2 (37% identical), TGIF1 (32% identical), PKNOX2 (20% identical), MEIS2 (19% identical), MEIS3P2 (18% identical), MEIS3 (17% identical), PKNOX1 (16% identical), MEIS1 (15% identical), PBX3 (14% identical), PBX1 (14% identical), PBX2 (13% identical), and 1 more.
Diseases named in the same sentence as TGIF2LX in open-access papers:
TGIF2LX is named in the same sentence as 2 diseases in open-access papers, as found by Europe PMC text mining. Sharing a sentence is not in itself a finding about the gene and the disease. The quoted sentences say what the papers report.
colon adenocarcinoma (1 paper, 2023). "Overexpression of the gene has been shown to inhibit proliferation and angiogenesis in colon adenocarcinoma, thus suggesting that TGIF2LX could have a tumor suppressor role." (PMID 36901898, 2023).
tumor (3 papers, 2020 to 2024). "However, these scenarios are modified with tumor suppressors such as the TGFβ-induced factor 2-linked X (TGIF2LX)." (PMID 33511135, 2020). "In the presence/absence of TGIF2LX, Nir2 acts as a tumor suppressor and Nir1 acts as a proto-oncogene, respectively." (PMID 33511135, 2020).